PKD1 (polycystin 1, transient receptor potential channel interacting)
Diseases named in the same sentence as PKD1 in open-access papers (continued):
Sharing a sentence is not in itself a finding about the gene and the disease.
cyst (continued). "Together these data indicate that, besides reversing the principal dysregulations considered the most proximal events in ADPKD pathogenesis, selective CaSR activation in PKD1 deficient cells restores altered mitochondrial function that, in ADPKD, is known to facilitate cyst formation." (PMID 30197885, 2018). "miR-17 expression was increased in cyst epithelia of both Pkd1-mutant and Pkd2-KO kidneys." (PMID 28205547, 2017). "Thus, deletion of miR-17∼92 inhibited cyst proliferation and disease progression in both Pkd1-KO and Pkd2-KO models." (PMID 28205547, 2017). "In ADPKD kidneys, somatic inactivation of PKD1 or PKD2 is a critical step in cyst formation." (PMID 28168444, 2017). "Our data show that TSC-PKD cross-talk is more complex than expected and that downregulation of the PKD1 gene product might play an important role in cyst formation in TSC." (PMID 26931735, 2016). "Pkd1 deletion on postnatal day 1 or 2 results in cysts arising from both the cortical and medullary regions, whereas deletion on postnatal days 3–8 results in primarily medullary cyst formation." (PMID 27356569, 2016). "Renal failure may occur as a consequence of repeated ablative treatments or as a consequence of cyst development, especially in patients with contiguous deletions in TSC2 and PKD1 (encodes polycystin-1) genes." (PMID 25258166, 2014). "The reason for the absence of cyst formation in the liver is not clear from our studies, because Col1a1(3.6)-Cre is expressed in the liver and results in excision of the Pkd1 flox allele in this tissue, similar to the pancreas and kidney." (PMID 23029375, 2012). "In addition to skeletal abnormalities, we found that Col1a1(3.6)-Cre-mediated deletion of Pkd1 resulted in cyst formation in the kidney and pancreas." (PMID 23029375, 2012). "Importantly, the frequency of cyst generation in kidneys of adult chimeric mice containing Pkd1(+/R+) iPSCs was significantly lower than that of adult chimeric mice with parental Pkd1(+/−) iPSCs, and indistinguishable from that of wild-type mice." (PMID 22347511, 2012). "Therefore, we perturbed the network map by inactivating Hnf4α in the context of Pkd1 inactivation and found that HNF4α in fact plays an important modulatory role in the early onset Pkd1 cyst model." (PMID 23209428, 2012). "While studies in normal cells established that the P1 oligo can stabilize wild-type Pkd1 transcripts, the critical question was whether the same strategy could rescue PC1 expression and cyst-pathogenic events in monoallelic, disease-relevant, mouse and human ADPKD cells." (PMID 41558825, 2026). "Our results in 2 rapidly progressive Pkd1 mouse models strongly support senicapoc’s ability to delay early-stage increases in renal cyst number and fibrosis with only 5 days’ treatment and its ability to slow cyst enlargement and fibrosis over a 10-day treatment course." (PMID 41122971, 2025). "Similarly, in an adult inducible Pkd1 knockout model, ANKMY2 deficiency reduced cyst burden." (PMID 41474822, 2025). "While the cadence and mechanisms of cyst formation due to cilia inactivation differ from polycystic kidney disease resulting from inactivation of Pkd1 or Pkd219, this observation does raise the intriguing possibility that Glis2 may be a common downstream effector for both mechanisms." (PMID 38693102, 2024). "Therefore, we hypothesized that local complement activation in Pkd1–/– kidneys drives tubular cell proliferation and cyst growth." (PMID 38912583, 2024). "The requirement of a minimum of 8 years follow-up imaging may have led to a bias toward having more PKD2 patients since some PKD1 patients reached endpoints excluding their participation before 8 years had elapsed such as end-stage kidney disease, cyst aspirations, and tolvaptan therapy." (PMID 38877066, 2024).
cyst (continued). "They observed a time-dependent effect of tolvaptan treatment on cyst size only in PKD1−/− and PKD2−/− tubuloids that were derived from a distinct subpopulation of CD24+ human kidney cells, which are hypothesized to represent an adult renal stem/progenitor population." (PMID 36831216, 2023). "Herein, we tested the potential beneficial effects of BA on 3D cyst growth and mitochondrial function in Pkd1-null kidney cells in vitro, and of BA alone and in combination with on key parameters of disease severity in kidneys and liver in conditional Pkd1 knockout mice." (PMID 36504724, 2022). "However, the already elevated cCDCA may have delayed turnover from the cilia to halt rapid cyst growth following early Pkd1 inactivation." (PMID 35832738, 2022). "Furthermore, inhibition of SIRT2 was found to reduce cyst growth in Pkd1 mouse kidneys." (PMID 35847973, 2022). "Thus, acute pharmaceutical Pkd1/2 derepression, including after cyst onset, attenuates murine PKD." (PMID 35965273, 2022). "Treatment with CPX-O in PKD mice inhibited cystogenesis as seen by the decrease of cyst index and cystic cell proliferation, and the improvement of renal function, suggesting that CPX-O may delay cyst growth through affecting ferroptosis process in Pkd1 mutant mice." (PMID 35847973, 2022). "To determine whether our kidney cell lines and conditional Pkd1 KO mouse model would be useful tools to evaluate the potential beneficial effects of BA in reducing cyst size or number in ADPKD, we first evaluated FATP2 protein expression in cells and tissues by immunoblot." (PMID 36504724, 2022). "Furthermore, PKD1-positive signals were observed in cyst-lining epithelial cells." (PMID 34980882, 2022). "Importantly, treatment with SMAC-mimetic reduced cyst growth in Pkd1 mutant mice." (PMID 35847973, 2022). "ADPKD is usually caused by mutations in the PKD1, PKD2, or GANAB genes which encode polycystin 1 (PC1) and polycystin 2 (PC2), respectively, and leads to excessive proliferation of the renal tubular epithelium, causing cyst formation and progressive renal interstitial fibrosis (RIF)." (PMID 35205236, 2022). "It is necessary, therefore, to identify the cellular subtypes in normal vs. Pkd1-mutant collecting ducts, and to systematically investigate the gene expression profiles (i.e., transcriptomes) of those cellular subpopulations during cyst initiation and progression, as we have done in this study." (PMID 36611841, 2022). "In addition, to address whether treatment with Pkd1-null cell EVs/exosomes could promote cyst formation in normal mice, we treated Pkd1flox/+:Pkhd1-Cre mice with Pkd1-null cell EVs/exosomes or PBS from postnatal day 7 (P7) to 3-month old." (PMID 34315885, 2021). "Thus, the cyst development in Dicer knockout mice may result from the modulation of PKD1 gene via miR-200." (PMID 33809516, 2021). "However, deletion of miR-214 in Pkd1 or Pkd2 mouse model aggravates the cyst growth." (PMID 33809516, 2021). "Mutations in PKD1 and PKD2 cause cyst formation through unknown mechanisms." (PMID 34301992, 2021). "However, renal Pparg expression only starts after E14.552, suggesting that either extra-renal effects (i.e. on the correction of cardiac defects and/or on subcutaneous oedema) or other pioglitazone targets explain the cyst inhibiting effects in the Pkd1−/− embryos." (PMID 32015419, 2020). "Our results suggest that p68 plays an important role in regulating the transcription of the PKD1 gene in ADPKD, the expression and maturation of miRNAs, the expression of fibrotic markers and the activation of PKD associated signaling pathways to promote cyst growth and renal fibrosis in ADPKD." (PMID 32724471, 2020). "The lack of a second mutation in either PKD1 or PKD2 prompted us to test for the presence of other somatic mutations that might explain cyst formation." (PMID 32163234, 2020). "We did not detect additional somatic mutations in PKD1 in individual cyst‐derived TEC lines." (PMID 32163234, 2020).
cyst (continued). "Finally, we applied conditional KO to PKD1 mutagenesis to verify in detail the mechanism of cyst formation according to the “two-hit” hypothesis." (PMID 31822676, 2019). "Conditional repression of either Pkd1 (Pax8rtTA; TetO-cre; Pkd1fl/fl) or Pkd2 (Pax8rtTA; TetO-cre; Pkd2fl/fl) results in kidney cysts within 10 weeks after the start of doxycycline induction, suggesting that expression of both genes is necessary to prohibit cyst development in mature mice." (PMID 29443690, 2018). "However, our results do not exclude a role for PI3K in PKD patients, where cyst growth is driven by mutations in the PKD1 or PKD2 gene." (PMID 28644734, 2017). "Together with the findings from the investigations in cells with a heterozygous PKD1 mutation, this result suggests that the mitochondria of cyst-derived cells with a PKD1 heteroplasmic mutation are not normal but exhibit cAMP-PKA-stimulated mitochondrial oxygen consumption." (PMID 28993480, 2017). "Since cyst-lining cells lose expression for Nek1, we suggest that stochastic inactivation of Nek1 is required for the manifestation of the PKD phenotype, as it is in humans and animals with heterozygous germ line mutations in PKD1 or PKD2 to manifest autosomal dominant PKD." (PMID 25030234, 2014). "Therefore, we speculate that the paucity of cortical cysts in the early stages of cyst formation, and the increased severity of cystic disease in double Hnf4α/Pkd1 knockout might reflect a protective role of HNF4α." (PMID 23209428, 2012). "In contrast, MTTV-Cre-mediated conditional deletion of Pkd1 results in liver cysts by 10 weeks-of-age, suggesting that the lack of liver cysts in our study was a consequence of limitations of the Col1a1(3.6)-Cre or the need for additional time for cyst development in the liver." (PMID 23029375, 2012). "Similarly, data from mice with mutations in polycystic kidney disease genes Pkd1, Pkd2, and Pkhd1 are conflicting and suggest that loss of oriented cell division alone does not initiate cyst formation." (PMID 23351924, 2012). "As these cells were not derived from cystic epithelium, we would not expect them to have further somatic mutations of PKD1 that may be important for cyst development." (PMID 22142803, 2011). "In vivo base substitution of this motif stabilizes Pkd1 messenger RNA and increases polycystin-1 (PC1) protein levels, producing a robust reduction in cyst growth and preservation of kidney function in mouse models." (PMID 41558825, 2026). "In another late-onset ADPKD mouse experiment, MCP-1 was up-regulated after Pkd1 knockout, and pharmacologic inhibition of MCP-1 receptor CCR2 (INCB3344) slowed cyst growth." (PMID 41431718, 2026). "Disruption of this site—either genetically, through precise base editing, or transiently, with steric-blocking oligonucleotides—stabilizes Pkd1/PKD1 transcripts, elevates PC1 protein, and attenuates cyst growth in mouse and human models." (PMID 41558825, 2026). "CRISPR-Cas9 technology was employed to knock out the PKD1 or PKD2 genes in these tubuloids, followed by drug treatments to induce cyst formation." (PMID 40002937, 2025). "In PKD1 or PKD2 mutant organoids, single-cell sequencing can identify cell populations including cyst wall epithelial cells, fibroblasts, and endothelial cells." (PMID 41359105, 2025). "Treatment of Pkd1+/+ metanephroi with increasing SKA-111 concentrations led to dose-dependent cystogenesis and > 2-fold increased percentage of cyst area (cystic index)." (PMID 41122971, 2025). "Hydroxyfasudil, a broadly selective inhibitor of both isozymes, reduced cyst expansion in both human PKD1 mutant 3D cyst assays and an inducible Pkd1−/− mouse model." (PMID 40253509, 2025). "Recently, anoctamin 1 (ANO1, also known as TMEM16A) has been identified as a Ca2+-activated Cl- channel that promotes fluid secretion in PKD1 or PKD2 knockout models, and its pharmacological inhibition slows cyst growth in cell cultures, as well as in mice." (PMID 40722835, 2025).
cyst (continued). "We identified KCa3.1/Kcnn4 as a major contributor to cyst enlargement that is upregulated in human ADPKD kidneys and in kidneys of all examined Pkd1 mouse models." (PMID 41122971, 2025). "For example, organoids with gene edits targeting polycystin-1 transient receptor potential channel interacting (PKD1/PC1) and polycystin-2 transient receptor potential cation channel (PKD2/PC2) can simulate cyst formation and related disease characteristics." (PMID 41359105, 2025). "The similar responses of Pkd1–/– metanephroi to both senicapoc and TRAM-34 support important contribution(s) of KCa3.1 function to cyst enlargement in metanephroi." (PMID 41122971, 2025). "These phenomena were also manifested in PKD1 (RC/RC) and PKD2 (WS25/−) mice, with MRTF translocation and overexpression occurring predominantly in dilated tubules and the cyst-lining epithelium, respectively." (PMID 38891116, 2024). "Recent studies have shown that the loss of PKD1 in mice alters the biomechanical properties of the basement membrane of renal tubules in a cilia-dependent manner, ultimately resulting in distal renal tubule dilation and cyst formation independent of cell proliferation." (PMID 39451240, 2024). "We have provided evidence that the double conditional knockout of PKD1 and SMYD3 delays cyst growth, improves renal function, and normalizes PKD-associated signaling pathways and cell cycle effectors." (PMID 38540216, 2024). "In collecting duct-specific Pkd1 KO mice, HL156A was found to inhibit cyst growth, reducing both the number and size of cysts." (PMID 39062520, 2024). "To assess the cyst-inhibitory effect of HL156A in vivo, we generated Pkd1 conditional knockout (KO) mice with aquaporin 2 (AQP2)-Cre, which selectively expresses Cre recombinase in the collecting duct." (PMID 39062520, 2024). "EVs derived from cystic renal epithelia cells would promote cyst formation in ADPKD by lowering the amount of polycystin 1 in the cystic kidneys, affecting the biology of PKD1 heterozygous renal epithelial cells." (PMID 37762196, 2023). "CFTRinh-172 or Ph-GlyH-101 reduced the cyst growth of renal MDCK cells in a metanephric mouse kidney model and a rapidly progressive neonatal Pkd1 knockout mouse model." (PMID 37686084, 2023). "In ADPKD, after knockdown of Pkd1 or Pkd2, C-C motif chemokine ligand 2 (CCL2) was highly upregulated at the onset of cyst formation." (PMID 37583898, 2023). "The molecular changes in the interaction between PKD1 and PKD2 genes increase cell proliferation and fluid secretion, mechanisms at the basis of cyst formation." (PMID 37372416, 2023). "In Pkd1 miRNA transgenic mice, MET resulted in faster cyst growth, worse renal function and lactate accumulation." (PMID 37653564, 2023). "The evidence linking Pkd1 and Pkd2 to JNK/AP-1 activity led us to ask what role JNK signaling plays in cyst formation and disease progression downstream of polycystin mutations." (PMID 35253003, 2022). "We find that eliminating the miR-17 motif is sufficient to improve Pkd1 mRNA stability, raise Polycystin-1 (PC1) expression, and ameliorate cyst growth in cellular, ex vivo, and mouse PKD models." (PMID 35965273, 2022). "After treatment, kidney organoids derived from PKD1 hiPSCs lines showed a severe increase in cystogenesis, while CRISPR-corrected isogenic controls showed marginal cyst formation." (PMID 36120564, 2022). "In Pkd1-miR Tg mice, the immunostaining of P2X7 receptors was most evident in the cyst lining epithelium both at the ages of postnatal day 30 (P30) and P60." (PMID 35955634, 2022). "An integrated analysis of miRNA and RNA-sequencing was employed in to investigate the miRNA profiles correlated with the severity of cyst development in two ADPKD models, kidney-specific Pkd1 or Pkd2 KO mice, at three time points, P1, P3, and P7." (PMID 34901057, 2021).
cyst (continued). "In this study, we identified obacunone from a library of natural antioxidant compounds, which showed cyst inhibitory effect in Madin-Darby canine kidney (MDCK) cyst model, embryonic kidney cyst model and kidney-specific Pkd1 knockout mouse (PKD) model." (PMID 35052542, 2021). "Then, by knocking down the PKD1 or PKD2 genes, these investigators observed cyst formation from kidney tubules." (PMID 34339420, 2021). "Both miR-214 and DNM3OS are upregulated in cystic kidneys from Pkd1 and Pkd2 mouse models, and human ADPKD, specifically in interstitial cells in the cyst microenvironment." (PMID 33809516, 2021). "Autophagic influx is inhibited in Pkd1 knockout mice (Pkd1−/−), Han:SPRD Cy/Cy rats and congenital polycystic kidney (cpk) mice, and induction of autophagy has been found to suppress cyst growth." (PMID 33809516, 2021). "Next, they investigated the effect of Hh signaling on the cyst by using the animal model; PKD1Cre; ROSALSL−GFP−SMO−M2 mice that expressed GFP-fused form of SMO along with deleted PKD1." (PMID 33308138, 2020). "The authors found that treatment of PKD1 patient cells and an inducible, kidney specific Pkd–/– mouse model with the ROCK inhibitor hydroxyfasudil reduced cyst size over 7 days of treatment." (PMID 33392209, 2020). "We showed in the past that cyst‐lining epithelia have intense nuclear YAP localization, both in Pkd1‐mutant mouse models and in ADPKD patients." (PMID 32592332, 2020). "They induced a PKD1 or PKD2 knock-out in hESC cells using the CRISPR/Cas9 technology and observed tubular cyst formation in derived kidney organoids." (PMID 32630605, 2020). "Here, we generate PKD1 KO or mosaic monkeys with various degrees of cyst formation by using CRISPR/Cas9 technology, and reveal the lineages of cyst epithelial cells." (PMID 31822676, 2019). "Clinically identified pathogenic mutations in either PKD1 or PKD2 were thought to result in abnormal PKD1/PKD2 channel function and dysregulated cilium signaling, ultimately initiating cyst formation." (PMID 29899465, 2018). "Accordingly, a previous study demonstrated that metformin inhibited cyst growth in Madin–Darby canine kidney (MDCK) cells and Pkd1 conditional knockout mice." (PMID 28769124, 2017). "However, the relevance of this finding to ADPKD is unclear because whether miR-17 can modulate cyst growth when Pkd1 or Pkd2 are already mutated has not been studied." (PMID 28205547, 2017). "While VPA treatment in Pkd1 knockout mice slightly decreased cyst formation, TSA reduced cyst formation in Pkd1 mutant embryos." (PMID 23052657, 2013). "Other groups have similarly identified developmental windows in which inactivation of Pkd1 or other cystogenes (Kif3a and Tg737, HNF-1β) leads to early- or late-onset cyst development." (PMID 23209428, 2012). "Deregulation of PKD1 or PKD2-coding polycystin protein level results in initiation of cyst formation, followed by several signaling pathways that mediate cyst growth and expansion." (PMID 22347511, 2012). "We identified changes in gene expression related to cyst growth such as components of MAPK (e.g. Map3k12, Fgf10, Prkcb, Traf2) and TGF-β (e.g. Pitx2) signaling that were up-regulated in the Pkd1-/- animals." (PMID 21518438, 2011). "Similarly, a recent study in which a Pkd1-inducible mouse model was treated with the nephrotoxicant DCVC after Pkd1-gene inactivation showed that unrestricted cellular proliferation after injury is not the underlying mechanism for cyst formation." (PMID 20813037, 2010). "Organoids generated from CRISPR-edited iPSCs harboring mutations in PKD1 or PKD2, as well as those derived from ADPKD patient samples, can spontaneously form cyst-like structures without the need for exogenous manipulation." (PMID 40801635, 2025). "The current study establishes that a plant-based WG diet mitigates kidney function decline, inflammatory agitation, and cyst-bearing effects of an animal-based casein diet in mice lacking Pkd1." (PMID 40493450, 2025).